OR10G8 (olfactory receptor family 10 subfamily G member 8)
Description:
Odorant receptor.
Synonyms: OR11-274; OR11-282
Tractability: Antibody: UniProt places it where antibodies can reach, with medium confidence; UniProt predicts a signal peptide or a membrane-spanning region; its Gene Ontology location is reachable by antibodies, with medium confidence.
Gene: Protein-coding gene on chromosome 11 (124,026,798 to 124,030,634, forward strand). Ensembl gene ENSG00000234560.
Subcellular location: Cell membrane
Pathways (Reactome):
Sensory Perception: Expression and translocation of olfactory receptors
Gene Ontology:
Molecular function: olfactory receptor activity; G protein-coupled receptor activity
Biological process: detection of chemical stimulus involved in sensory perception of smell; G protein-coupled receptor signaling pathway
Cellular component: plasma membrane; membrane
Genetic constraint (gnomAD): Loss-of-function variants: 1 observed, 0.38 expected, observed/expected ratio (o/e) 2.63. That is too few expected variants to judge how well the gene tolerates losing a copy. Missense variants: 386 observed, 392.44 expected, observed/expected ratio (o/e) 0.98, 90% interval 0.9 to 1.07. Synonymous variants: 173 observed, 164.01 expected, observed/expected ratio (o/e) 1.05, 90% interval 0.93 to 1.2.
Homologues: Orthologues: macaque OR10G8 (90% identical), dog OR10G9 (84% identical), dog OR10G9C (84% identical), mouse Or10g9 (83% identical), mouse Or10g7 (82% identical), rat Or10g9 (82% identical), mouse Or10g9b (82% identical), rat Or10g9b (82% identical). Paralogues in human: OR10G7 (88% identical), OR10G9 (88% identical), OR10G4 (87% identical), OR10G2 (55% identical), OR10G6 (51% identical), OR10D3 (49% identical), OR10G3 (49% identical), OR10S1 (49% identical), OR2D3 (46% identical), OR2F1 (45% identical), OR2F2 (45% identical), OR2C3 (43% identical), and 80 more.